THBS1 (thrombospondin 1)
Diseases named in the same sentence as THBS1 in open-access papers (continued):
Sharing a sentence is not in itself a finding about the gene and the disease.
gastric cancer (continued). "Researchers discovered communications between CAFs and gastric cancer cells via integrin receptor interactions with collagen, fibronectin, thrombospondin 1 (THBS1) ligands, and leucine rich repeat containing G protein-coupled receptor 4 (LGR4)- R-spondin 3 (RSPO3), which regulate stemness." (PMID 36154923, 2022). "In summary, HEYL, MMP7, THBS1, and KRT17 are not only highly expressed in gastric cancer, but also associated with poor prognosis and may be potential prognostic biomarkers." (PMID 34157940, 2021). "However, its angiostatic function has also been demonstrated in pancreatic and gastric cancers via the induction of thrombospondin 1, a potent angiogenic inhibitor producer." (PMID 34680504, 2021). "Here, we found that THBS1 methylation levels in preoperative serum or peritoneal fluid can accurately predict peritoneal dissemination and suggest a poor prognosis in patients with gastric cancer." (PMID 34390026, 2021). "The FGF7/FGFR2 signaling cascade has been found to upregulate thrombospondin 1 (THBS1), promoting invasion and migration of gastric cancer cells." (PMID 38491511, 2024). "Among the enriched pathways related to poor prognosis, five theranostic markers of interest were identified as deregulated and enriched in gastric cancer, including vWF, FN1, THBS1, PCDH7, and F5." (PMID 39456895, 2024). "In addition, increasing studies suggest that THBS1 is a prognostic biomarker of cancers and/or plays complex roles in various cancer types, such as glioblastoma, papillary thyroid cancer, gastric cancer, esophageal squamous cell carcinoma, and acute myeloid leukemia." (PMID 37708239, 2023). "Then, gastric cancer cell lines were analyzed, and SERPINE1 and THBS1 were found to be relatively higher in metastatic tumor cell lines." (PMID 35372476, 2022). "The TIMER was used to explore the immunological microenvironment and identified correlations between levels of immune infiltration and expressions of the THBS1 and SERPINE1 in gastric cancer." (PMID 35372476, 2022). "In human gastric cancer cells, FGF7-FGFR2 signaling increased PI3K-AKT-mTOR signaling, which upregulated invasive/migratory glycoprotein thrombospondin 1 (THBS1)." (PMID 34068954, 2021). "In summary, FBN1, FN1, HGF, MMP9, THBS1, and VCAN can be used as new target genes to observe the prognosis of gastric cancer." (PMID 33014013, 2020). "THBS1 and SERPINE1 were significantly differentially expressed in the two types of gastric cancer, and may have potentially important functions." (PMID 35372476, 2022). "Expression of THBS1 and SERPINE1 in early gastric cancer and advanced gastric cancer." (PMID 35372476, 2022). "In gastric cancer, THBS2 is positively correlated with THBS1, THBS3, and THBS4." (PMID 34804159, 2021). "It was finally confirmed that HEYL, MMP7, THBS1, and KRT17 may be potential biomarkers of gastric cancer." (PMID 34157940, 2021). "Moreover, THBS1 and UCHL1 methylation in the serum was closely correlated with worse clinical outcomes in gastric cancer patients." (PMID 26550574, 2015). "Further, in gastric cancer, as EBV-induced hypermethylation targets and silences key tumor suppressor genes including APC, RASSF1, BRCA1, THBS1, and CDKN2A, DNA methyltransferase inhibitors may also serve as a new therapeutic treatment for patients with EBV-positive gastric cancer." (PMID 37234978, 2023). "The present study investigated whether methylated THBS1 in circulating cell‐free DNA from preoperative peritoneal lavage fluid (PPLF) and peripheral blood could be used as a potential biomarker for predicting peritoneal dissemination in gastric cancer (GC) patients." (PMID 34390026, 2021).
glioblastoma (41 papers, 2009 to 2025). The most malignant astrocytic tumor (WHO grade IV). "We undertook a systematic study focused on the matricellular protein Thrombospondin-1 (THBS1) to uncover molecular mechanisms underlying the role of THBS1 in glioblastoma (GBM) development." (PMID 30850588, 2019). "Moreover, THBS1 is linked to inflammatory and immune responses in glioblastoma, reinforcing its role as a critical factor in tumor progression." (PMID 41432874, 2025). "In glioblastoma, THBS1 is upregulated in high-grade gliomas and associated with poor prognosis." (PMID 39304722, 2024). "In addition, analysis of two additional patient glioblastoma cultures (PriGO7A and 9A) showed that their susceptibility to senescence induction by serum roughly corresponded to their basal levels of thrombospondin 1 expression." (PMID 28526854, 2017). "In preclinical models, knockout of Thrombospondin-1 (TSP1/Thbs1) in glioblastoma cells suppresses synaptogenesis and glutamatergic neuronal hyperexcitability." (PMID 40404658, 2025). "The suppression of THBS1 expression effectively curbs tumor cell invasion and proliferation in glioblastoma." (PMID 41019041, 2025). "THBS1 has been recognized as a key biomarker for predicting the mesenchymal subtype of glioblastoma and aiding in histopathological diagnosis." (PMID 41432874, 2025). "Specific inhibition of the THBS1/CD47 interaction using an antagonist peptide decreases cell invasion in glioblastoma." (PMID 41019041, 2025). "The down-regulation of THBS1 expression in glioblastoma multiforme suggests a potential role for THBS1 promoter methylation and transcriptional silencing in this process." (PMID 39273281, 2024). "More recently, THBS1 was recognized as a central regulator of glioblastoma invasiveness, as a bioinformatics analysis predicted its high connectivity with collagens, TGFβ1, and integrins." (PMID 39304722, 2024). "THBS1 expression was downregulated in glioblastoma multiforme (GBM), which may be implicated in THBS1 promoter methylation and transcriptional silencing." (PMID 38203613, 2023). "Pharmacological inhibition of thrombospondin-1 using the FDA-approved drug gabapentin decreases glioblastoma proliferation." (PMID 37138086, 2023). "Possibly, the upregulation of ThBs1 seen in the specimens of treated glioblastomas is an important driver of tumor progression despite treatment, and an interesting target for future additional therapies." (PMID 36717781, 2023). "TGFβ1 induces THBS1 (thrombospondin-1) expression via Smad3, which contributes to invasive behavior during glioblastoma expansion; TGF-β also stimulates both THBS1 and CISP/THBS2 synthesis by bovine adrenocortical cells." (PMID 36535930, 2022). "THBS1 (degree = 4), a cell adhesion glycoprotein that mediates cell-cell and cell-matrix interactions, has been suggested as a target for glioblastoma." (PMID 35913978, 2022). "THBS1 was reported to contribute to the invasive behavior during glioblastoma (GBM) development through TGFβ canonical pathway." (PMID 34575042, 2021). "The methylation status of MGMT and THBS1 in CSF was also able to independently predict PFS of glioblastoma patients." (PMID 34208598, 2021). "Exosomes released from hypoxic U87MG glioblastoma cells contain an elevated level of some proteins like thrombospondin-1 (TSP1), VEGF, and protein-lysine 6-oxidase (LOX) that promote growth, metastasis, and angiogenesis of tumor." (PMID 33302971, 2020). "This study showed modulation of several genes related to cell adhesion and migration, such as CTGF, COL3A1, SERPINE1 and THBS1, all of which we found to be modulated in glioblastoma cells." (PMID 30850678, 2019). "High thrombospondin 1 expression appears to be a general feature of the mesenchymal subtype in glioblastoma, based on analysis of the TCGA database." (PMID 28526854, 2017).
glioblastoma (continued). "Here we have studied the short term responses of primary glioblastoma cells to serum, showing that serum induces a thrombospondin 1-dependent activation of TGFβ pathway signalling in these cells." (PMID 28526854, 2017). "Here, the authors employ human single-cell RNA-seq, spatial transcriptomics, and a preclinical mouse model to show that glioblastoma cell-derived synaptogenic factor Thrombospondin-1 promotes neuronal circuit remodeling and regional immunosuppression, highlighting a potential therapeutic target." (PMID 40404658, 2025). "The suppression of radixin upregulates thrombospondin-1 (TSP-1) and E-cadherin and downregulates matrix metalloproteinase (MMP) -9 in glioblastoma U251 cells, which may be associated with cell migration and invasion." (PMID 39457653, 2024). "Furthermore, glioblastoma remodels human neural circuits by secreting synaptogenic factors (such as thrombospondin-1 and glypican-3), which promote functional tumor and neuronal connectivity while reducing patient survival." (PMID 39268034, 2024). "Moreover, specific inhibition of the THBS1/CD47 interaction by an antagonist peptide attenuates cell invasion glioblastoma." (PMID 34804159, 2021). "THBS1 is a powerful anti-angiogenesis protein in glioblastoma." (PMID 27716259, 2016). "Thus, the three type I repeats (3TSR) inhibit tumor growth in glioblastoma, whereas the fragment 167–569, a thrombospondin-1 active peptide, which includes the procollagen homology domain and 3TSR, stimulates tumorigenicity, although it inhibits neovascularization." (PMID 35054787, 2022). "In 2021, Yao and colleagues reported that overexpression of Thrombospondin 1 (THBS1) promotes the proliferation, migration, and invasion of glioblastoma cells, while knockdown of MYH9 reverses these effects." (PMID 39988672, 2025). "Elevated expression of THBS1 within HFC regions was confirmed by protein-level analysis using HFC and LFC patient-derived glioblastoma biopsy tissues." (PMID 37138086, 2023). "Recent literature described THBS1 as a TGF-ß target and a factor regulating tumor cell invasion in glioblastoma and oral squamous carcinoma." (PMID 36868311, 2023). "We identified the following five proteins that were present in all samples, both glioblastoma-derived EVs and HPA-derived EVs: THBS1, FN1, TGFBI, ACTN4, and LGALS3BP." (PMID 35454889, 2022). "In brain tumors such as glioblastoma, promoter hypermethylation of several genes (MGMT, p16INK4a, TIMP-3, and THBS1) has been detected at high frequencies in serum and CSF." (PMID 34208598, 2021). "Our study shows the cells grown in 3D-GMH with serum overexpress and secrete CXCL1, CXCL5, IGFBP2, PTX3, THBS1, VEGFA, and VCAM1—all genes expressed in perivascular or perinecrotic zone of glioblastoma tissues that are hotspots for immune cells." (PMID 34489494, 2021). "In particular, EVs secreted from glioblastoma U87MG cells are transferred into microglia MG6 cells, where they downregulate the expression of thrombospondin 1 (Thbs1), a negative regulator of angiogenesis." (PMID 34188113, 2021). "THBS1 was upregulated in ESCA (esophageal carcinoma), GBM (glioblastoma multiforme), and PAAD (pancreatic adenocarcinoma) and downregulated in 13 types of cancers, including LUSC (lung squamous cell carcinoma) and KICH (kidney chromophobe)." (PMID 34804159, 2021). "Glioblastoma cells secrete, in vitro and under hypoxic conditions, exosomes that contain protein-lysine 6-oxidase (LOX), thrombospondin-1 (TSP1), vascular endothelial growth factor (VEGF) and metalloproteinase with thrombospondin motifs 1 (ADAMTS1)." (PMID 32824183, 2020). "Clearly, cells expressing IRE1α RNase mutants heightened the expression of ECM markers characteristic of glioblastoma malignancy or invasion, including fibrillar collagens, the collagen cross-linker LOX and the proteins THBS1, YKL-40, DCN and LAMA4." (PMID 26325176, 2015).
Obesity (32 papers, 2011 to 2025). Accumulation of substantial excess body fat. "Elevated Thbs1 levels have been linked to adipose tissue inflammation in obesity and high-fat diet models, as well as increased blood pressure in hypertensive rats." (PMID 40277904, 2025). "Knocking out Thbs1 in AT can inhibit tissue inflammation caused by obesity and improve tissue insulin sensitivity." (PMID 38764083, 2024). "We were intrigued by the identification of Thbs1 as a putative let-7a-5p target, a functional gene linked to obesity, lipid metabolism, and adipose biology." (PMID 38255968, 2024). "Thrombospondin-1 (THBS1) is an obesity-associated matricellular protein linked with muscular damage in genetic myopathies." (PMID 38954467, 2024). "THBS1 is therefore a necessary mediator of diaphragm stromal remodeling and contractile dysfunction in overnutrition and a potential therapeutic target in obesity-associated respiratory dysfunction." (PMID 38954467, 2024). "Given the improved tissue architecture observed in HFD-fed KO versus WT mice, we predicted that Thbs1 ablation would also protect the diaphragm from obesity-associated mechanical dysfunction." (PMID 38954467, 2024). "Angiogenesis markers, such as angiopoietin 1 (Angpt1) and thrombospondin 1 (Thbs1), are associated with obesity." (PMID 36293486, 2022). "We previously reported that leptin, at concentrations relevant to obesity and diabetes, has a direct stimulatory effect on the proatherogenic matricellular protein, thrombospondin-1 (TSP-1), implicated in atherosclerosis." (PMID 34064112, 2021). "Therefore, Thbs1 ablation protects the diaphragm from obesity-associated contractile force reduction." (PMID 38954467, 2024). "On the whole, THBS1 facilitates obesity-associated expansion of the diaphragm FAP pool, inducing a fibrogenic transcriptomic signature typified by TGF-β–dependent gene expression and enrichment of a THY1+ subpopulation previously linked to tissue-level remodeling." (PMID 38954467, 2024). "Thbs1 ablation protects mice from obesity-associated deterioration of diaphragm motion." (PMID 38954467, 2024). "The influence of Thbs1 on cardiovascular diseases is complex and multifactorial, since its activity depends on the vessel type, the stage of the lesions, and associations with obesity, diabetes, or other metabolic diseases." (PMID 35455758, 2022). "Interestingly, PILRA has also been found to be decreased in skeletal muscle of patients with obesity and T2D, and thrombospondin 1 has been linked to β-cell lipotoxicity and diabetic retinopathy, suggesting an important role of these sex-specific changes in diabetes pathogenesis." (PMID 38032738, 2024). "One example is thrombospondin 1 (THBS1), a ‘matricellular’ protein that has shown to be increased in individuals with obesity and T2D (in tissue and plasma)." (PMID 40846464, 2025). "In contrast, among the genes interacting with key adipogenic factors, LPXN, TNC, THBS1, and OGG1 have been directly associated with obesity and fat accumulation." (PMID 40130165, 2025). "THBS1 is required for this shift, since the expression of numerous obesity-induced, ECM-related FAP genes (such as Fbn1, Col3a1, and Adamts5) is markedly blunted in HFD-fed KO mice." (PMID 38954467, 2024). "Thbs1 is up-regulated in adipose tissue under obesity (Section 2.3), and in this study, it was negatively associated with let-7a-5p expression." (PMID 38255968, 2024). "Despite similar weight gain, Thbs1–/– mice were protected from these transcriptomic changes and from obesity-induced increases in diaphragm adiposity and ECM deposition." (PMID 38954467, 2024). "Our in vitro data demonstrate an analogous effect on FAPs, as THBS1 concentrations comparable to those found in humans with obesity promote their proliferation." (PMID 38954467, 2024). "Thbs1-knockout (Thbs1–/–) mice are protected from obesity-induced fibro-adipogenic diaphragm remodeling and respiratory dysfunction." (PMID 38954467, 2024).
Obesity (continued). "Our findings demonstrate that anatomic remodeling and contractile dysfunction of the diaphragm are interrelated, Thbs1-dependent obesity complications." (PMID 38954467, 2024). "Conversely, Thbs1-null mice are protected against obesity-induced metabolic alterations, largely by preventing fibrotic muscle degeneration." (PMID 38788527, 2024). "A study suggested that THBS1 in obesity or type 2 diabetes mellitus was highly expressed than healthy controls." (PMID 36544488, 2022). "Thrombospondin-1 (THBS1) is elevated in fibrotic liver diseases including NASH, and THBS1 from macrophages is assumed to foster NASH in the context of obesity." (PMID 35681524, 2022). "Thbs1 -/- mice are resistant to obesity following ingestion of a high-fat diet and display normal levels of leptin, an important adipokine associated with increased body weight." (PMID 33854480, 2021). "The upregulation of THBS1 can be stimulated by glucose, and the overexpression of THBS1 contributes to obesity-induced tissue inflammation and the development of metabolic syndrome." (PMID 35127552, 2021). "In accordance with earlier findings, we previously demonstrated that leptin at concentrations relevant to obesity upregulates a potent proatherogenic protein, thrombospondin-1 (TSP-1) expression, in human and murine aortic SMC primary cultures." (PMID 34064112, 2021). "A number of novel obesity candidate genes were also identified (Thbs1, Ppp1r3d, Tmepai, Trp53inp2, Ttc7b, Tuba1a, Fgf13, Fmr) that have inferred roles in fat cell function." (PMID 21915269, 2011). "This ‘boost’ of adipogenic potential in FAPs mediated by THBS1 could further promote and perpetuate the cycle of fibro‐fatty deposition in obesity." (PMID 40846464, 2025). "The expression of Thbs1 is positively correlated with obesity and IR." (PMID 38764083, 2024). "Using the Thbs1-null state as an interrogating probe, we aimed to identify FAP subtypes involved in obesity-induced diaphragm remodeling and determine whether Thbs1 ablation could ameliorate attendant contractile impairment." (PMID 38954467, 2024). "THBS1 is also elevated in obesity and is an adipocyte-derived cytokine (adipokine)." (PMID 37265843, 2023). "CD47 -/- mice, as well as Thbs1 -/- mice, are resistant to obesity." (PMID 33854480, 2021). "Moreover, thrombospondin 1 has been proposed as a novel marker related to obesity and metabolic syndrome." (PMID 32485856, 2020). "An alternative explanation is that THBS1 could directly impair myofiber function in obesity." (PMID 38954467, 2024). "In sum, animals lacking Thbs1 are protected from obesity-associated diaphragm motion compromise." (PMID 38954467, 2024). "In conclusion, our study highlights the physiological significance of let-7a-5p in lipid accumulation and suggests that the let-7a-5p/Srebf2 and let-7a-5p/Thbs1/PI3K-AKT-mTOR axes may represent potential mechanisms for controlling lipid accumulation in obesity." (PMID 38255968, 2024). "Therein, THBS1 is a putative regulator of FAP phenotype and consequent diaphragm remodeling in obesity." (PMID 38954467, 2024). "In a diet-induced animal model of obesity, the influx of CD68+ macrophages and angiogenesis in Thbs1 -/- adipose tissues was similar to that of the control tissues." (PMID 33854480, 2021). "At least 4/15 genes containing ≥6 differentially methylated CpG sites had a potential role in obesity and/or related traits (PRKCZ, PRDM16, FOXP2, THBS1)." (PMID 25651499, 2015). "Our findings suggest that PVAT adipocyte progenitors may be a source of thrombospondin-1, and changes in its expression within these cells or other PVAT components could potentially trigger responses similar to those observed in obesity." (PMID 40277904, 2025). "Our findings indicate that the let-7a-5p/Srebf2 and let-7a-5p/Thbs1/PI3K-AKT-mTOR axes may be crucial in regulating animal lipid accumulation and may contribute to the development of new therapies for obesity." (PMID 38255968, 2024).